BDNF (brain derived neurotrophic factor)
Diseases named in the same sentence as BDNF in open-access papers (continued):
Sharing a sentence is not in itself a finding about the gene and the disease.
migraine (45 papers, 2012 to 2025). "The BDNF signaling pathway is frequently discussed in studies related to the pathophysiology and mechanisms associated with migraines." (PMID 40162625, 2025). "The BDNF variant rs2049046, located on the 5′ end of the same transcript, has been shown to have a strong correlation with migraine." (PMID 38213956, 2024). "Indication of genetic interaction in migraine predisposition has been previously shown, namely, our group had found a robust gene-gene interaction between BDNF and CGRP and between GABAA-R genes, in migraine susceptibility." (PMID 34126933, 2021). "BDNF was related to migraine susceptibility both in episodic and chronic forms, potentially by BDNF-induced pain-related neural plasticity, and its modulation by BHB can improve clinical symptoms." (PMID 34371817, 2021). "eNOS is also involved in endothelium, releasing VEGF and BDNF that are implicated in central sensitization during migraine attacks." (PMID 32516927, 2020). "According to the results of thee meta-analyses of over 1000 patients suffering from migraine, BDNF gene polymorphisms, rs6265 and rs2049046, are associated with common migraine in the Caucasian population; both data came from adult migraineurs." (PMID 33020432, 2020). "In conclusion, our meta-analysis suggested that BDNF rs6265 and rs2049046 polymorphism were associated with common migraine in Caucasian population." (PMID 28150221, 2017). "In this regard, it is noteworthy that the BDNF gene is differentially expressed in the rat after cortical spreading depression, the putative underlying mechanism of the migraine aura." (PMID 28507530, 2017). "And it requires further studies to evaluate the association of BDNF rs6265 and rs2049046 polymorphism with migraine in Asian population and other types of migraine." (PMID 28150221, 2017). "Our meta-analysis suggested that BDNF rs6265 and rs2049046 polymorphism were associated with common migraine in Caucasian population." (PMID 28150221, 2017). "BDNF, which is associated with the pathogenesis of migraine, shares a wide distribution in central nervous system, such as hippocampus, amygdala, and hypothalamus." (PMID 28150221, 2017). "The association between BDNF gene variant and migraine attracts more and more attention in recent years." (PMID 28150221, 2017). "Previous studies found that central BDNF can cause neuroplasticity and interact with molecules related to migraine." (PMID 28150221, 2017). "As these limitations can be partly overcome by combining data from relevant studies by meta-analytic methods, we herein conducted a systematic review and meta-analysis of published data to estimate the impact of BDNF rs6265 on migraine susceptibility." (PMID 28507530, 2017). "Main characteristics of the studies included in the meta-analysis of the association between brain-derived neurotrophic factor rs6265 and migraine." (PMID 28507530, 2017). "In the present study, we conducted a systematic review and meta-analysis of published data to quantitatively estimate the impact of BDNF rs6265 on migraine susceptibility." (PMID 28507530, 2017). "Summary of meta-analyses for the association of brain-derived neurotrophic factor rs6265 with migraine risk." (PMID 28507530, 2017). "The pooled results have indicated that BDNF rs6265 confers an increased risk for migraine, reaching significant level under the allelic or the dominant model of inheritance." (PMID 28507530, 2017). "A number of candidate gene studies have focused on the role of BDNF rs6265 as a risk factor for migraine; however, the results remain inconclusive." (PMID 28507530, 2017). "Odds ratio (OR) with corresponding 95% confidence interval (CI) was used to estimate the strength of association between BDNF gene rs6265 and rs2049046 polymorphism and migraine." (PMID 28150221, 2017). "Results of a recent case–control study suggest an interaction of CGRP and BDNF polymorphisms, contributing to migraine susceptibility." (PMID 22584531, 2012).
migraine (continued). "The glycolysis inhibitor 2-DG significantly inhibited the symptoms of migraine, and the underlying mechanisms included inhibition of microglia activation, inhibition of Iba-1/proBDNF/BDNF pathway, and the release of inflammatory and neurogenic inflammatory factors." (PMID 37090989, 2023). "Researchers have suggested that these associations of BDNF may play a significant role in modulating susceptibility of patients to migraine." (PMID 34991456, 2022). "To determine whether BDNF was related to migraine-associated hyperalgesia, we used ANA-12, a TrkB receptor inhibitor, in NTG mice." (PMID 31937253, 2020). "We next determined whether BDNF was related to migraine-associated hyperalgesia following treatment with ANA-12, a TrkB receptor inhibitor." (PMID 31937253, 2020). "Second, other pain-related genetic polymorphisms, such as BDNF rs2049046 and G-712A reported in migraine studies or OPRM1 A118G reported in PDM study, might also be potential candidates of genetic modulators of chronic pain-sculpted brain complexity." (PMID 30524221, 2018). "It has been reported that BDNF Val66Met may have roles in susceptibility for migraine, especially for migraine with aura (MA) subtype." (PMID 29896439, 2018). "Thus, it is proposed that NTG-induced neurogenic inflammation acts as an important cause for BDNF up-regulation in migraine attacks." (PMID 27875242, 2017). "The present meta-analysis supports that BDNF rs6265 may act as a genetic susceptibility factor for migraine." (PMID 28507530, 2017). "Based on these previous findings, the results of the present meta-analysis suggest that the Met allele of BDNF rs6265 may contribute to the development of migraine because of its detrimental influence on the central serotoninergic tone." (PMID 28507530, 2017). "As a candidate-gene association study, our hypothesis arose from the positive association between BDNF and migraine revealed in previous clinical researches." (PMID 28150221, 2017). "Whether the expression of BDNF rs6265 and rs2049046 polymorphism has any difference in different migraine types remains to unclear." (PMID 28150221, 2017). "In conclusion, our meta-analysis based on five case–control association studies suggested that rs6265 polymorphism of the BDNF gene may confer an increased susceptibility to migraine." (PMID 28507530, 2017). "Our findings suggest that reduced BDNF protein levels in the brain, which are to be expected in carriers of the Met allele of BDNF Val66Met polymorphism (rs6265A), may increase the likelihood of migraine." (PMID 28507530, 2017). "Hence interactions between CGRP and BDNF have been suggested to increase migraine susceptibility." (PMID 22584531, 2012). "While the specific mechanisms vary, many interventions exert their therapeutic effects by modulating key signaling pathways associated with migraine, including the NF-κB pathway, Nrf2 antioxidant pathway, and ERK/CREB/BDNF pathway." (PMID 38836002, 2024). "Overexpression of BDNF in the ventrolateral periaqueductal gray (vlPAG) decreases the severity of epileptic and migraine-like events in comorbid rats, indicating an analgesic effect by activating the BDNF-TrkB signaling pathway." (PMID 37450927, 2024). "There is a growing suspicion of BDNF’s involvement in the pathophysiology of migraine and cluster headaches, primarily because of its established interaction with calcitonin gene-related peptide." (PMID 38836002, 2024). "In migraine models, ATP administration triggers BDNF release, increases BDNF synthesis in the TNC, and decreases central sensitization symptoms." (PMID 37450927, 2024). "Many studies have shown that activated microglia can release more BDNF, which is involved in many neurological diseases including migraine." (PMID 37090989, 2023). "Previous studies have suggested that BDNF is a pain-modulator and activated microglia cells promote migraine by synthesizing and releasing BDNF." (PMID 37090989, 2023).
migraine (continued). "This study further shows that activated microglia facilitate migraine by synthesizing and releasing BDNF after epileptic seizures." (PMID 35382731, 2022). "In 2010, Tanure and colleagues demonstrated that BDNF serum levels are significantly elevated during migraine attacks." (PMID 34991456, 2022). "In summary, overexpression of BDNF in vlPAG decreased the severity of epileptic and migraine‐like events in comorbid rats, pointing to an antiseizure and analgesic effect via the activation of BDNF–TrkB signaling pathway." (PMID 35557046, 2022). "We next explored the protein expression of CX3CR1/FKN/proBDNF/BDNF to examine the effects of AZD8797 on migraine model rats after seizures at the molecular level." (PMID 35382731, 2022). "We also demonstrated that BDNF expression was regulated by the FKN/CX3CR1 axis in migraine model rats." (PMID 35382731, 2022). "Taking this into account, we aimed to investigate potential biomarkers associated with migraine in EM and CM patients with a special focus on PGE2, VEGF, NGF and BDNF." (PMID 34991456, 2022). "Regardless of the inverse or direct relationship between BDNF levels and propensity for migraine, these various levels of evidence emphasize the role of BDNF in nociceptive pathways." (PMID 34991456, 2022). "We also acknowledge that our study faced several limitations; the case-control nature of the study prohibited us from drawing conclusions about causality and directionality between migraine and NGF, BDNF, VEGF, and PGE2 peripheral blood levels." (PMID 34991456, 2022). "There is also evidence that aerobic exercise diminishes the burden of migraine with proposed mechanisms including upregulation of brain-derived neurotrophic factor (BDNF), improved neurovascular regulation, and modulation of endogenous pain fighting systems." (PMID 34125320, 2021). "Studies have shown that BDNF is increased during migraine attacks, and in cluster headache, and there is some genetic evidence suggesting a role of BDNF in migraine." (PMID 34239411, 2021). "Like CGRP, BDNF is elevated during migraine, suggesting that these two mediators act together in augmenting purinergic receptors in migraine." (PMID 32088764, 2020). "An increasing number of studies have suggested that BDNF is expressed in the trigeminovascular system and has a role in migraine pathophysiology." (PMID 31937253, 2020). "Some studies using models of hyperalgaesic priming have demonstrated a role for BDNF in mediating persistent pain in migraine and following acute inflammation, which suggests that BDNF expression overall can drive chronic pain." (PMID 29394316, 2018). "The inconsistent outcome between our study and others is probably related to the different time points when BDNF and TrkB expression were detected, or to the different inducers that evoke migraine and transient anterograde amnesia, respectively." (PMID 27875242, 2017). "The brain-derived neurotrophic factor (BDNF) gene rs6265 (Val66Met) and rs2049046 polymorphism has been found to be associated with migraine." (PMID 28150221, 2017). "Recently, a role of BDNF has been suggested in migraine pain, due to its interaction with calcitonin gene-related peptide (CGRP), a key vasodilating neuropeptide implicated in migraine pathogenesis." (PMID 28507530, 2017). "Consistent to our data, clinical studies exhibited that migraine patients have significantly higher BDNF serum level during migraine attacks, compared with headache-free intervals and healthy controls." (PMID 27875242, 2017). "We also found that BDNF serum level was higher in the female than male rats in migraine attacks, implying a more profound role in female rats." (PMID 27875242, 2017). "Using the ELISA method, we observed remarkable increase in serum BDNF level in migraine attack (P<0.01), compared to non-migraine control." (PMID 27875242, 2017).
migraine (continued). "BDNF serves as an important modulator of central and peripheral pain responses, but the role it has in migraine and its pathophysiology is incompletely understood." (PMID 27875242, 2017). "This meta-analysis evaluated the association between BDNF gene polymorphism and migraine and showed that BNDF rs6265 (G/A) and rs2049046 (A/T) polymorphism were associated with migraine in Caucasian population." (PMID 28150221, 2017). "Our main findings were BDNF is significantly elevated in patients with migraine and cluster headache compared with patients with tension-type headache and healthy controls." (PMID 22584531, 2012). "This prospective bi-center study aimed to analyze serum levels of BDNF in patients with primary headache disorders, i.e. migraine, cluster headache, and tension-type headache." (PMID 22584531, 2012). "In migraineurs, BDNF was significantly elevated during migraine attacks compared with headache-free periods (P < 0.01), tension-type headache (P < 0.05) and healthy controls (P < 0.001)." (PMID 22584531, 2012). "Recently, a role of BDNF in migraine and cluster headache pathophysiology has been suspected due to its known interaction with calcitonin gene-related peptide." (PMID 22584531, 2012). "Migraine patients revealed significantly higher BDNF serum levels during migraine attacks (n = 25) compared with headache-free intervals (n = 53, P < 0.01), patients with tension-type headache (n = 6, P < 0.05), and healthy controls (n = 22, P < 0.001)." (PMID 22584531, 2012). "In our study, pulmonary BDNF may act as a signal to initiate the activation of vagal sensory nerves, thereby further regulating migraines." (PMID 40162625, 2025). "Examination of BDNF levels following exercise in migraine patients still needs to be explored, however, serum BDNF levels tend to be higher during migraine attacks, which may contribute to the complex relationship between migraine and exercise." (PMID 40634879, 2025). "For instance, research on migraine pain has yielded mixed results, with some studies reporting lower serum BDNF levels during acute and chronic migraine, while others show higher BDNF levels during headache attacks compared to attack‐free periods." (PMID 40222813, 2025). "From a clinical perspective, there is a need for increased research emphasis on NLRP3 and BDNF, as this may offer more effective solutions for migraine treatment." (PMID 38836002, 2024). "Furthermore, the role of BDNF was explored in a rat model of status epilepticus, induced by intraperitoneal injection of lithium chloride-pilocarpine, and migraine, induced by repeated dural injections of inflammatory soup." (PMID 37569811, 2023). "The mechanism of exercise for migraine prophylaxis might include increased levels of beta-endorphin, endocannabinoid, and brain-derived neurotrophic factor in plasma after exercise." (PMID 36713835, 2023). "Glycolytic inhibitors may influence the occurrence of migraine through the Iba-1/proBDNF/BDNF pathway." (PMID 37090989, 2023). "When combined with our findings, it is reasonable to hypothesize that microglia- produced BDNF may play a vital role in the development of postepileptic migraine." (PMID 35382731, 2022). "In line with this hypothesis, our study supports this idea by showing that neurons activate microglia in the cortex/thalamic/sp5c via the FKN/CX3CR1 axis, which leads to enhanced BDNF production in migraine model rats following an epileptic episode." (PMID 35382731, 2022). "AZD8797 (a CX3CR1 inhibitor) prevented the worsening of hyperalgesia and microglial activation in migraine model rats after seizures, while FKN infusion in migraine model rats exacerbated hyperalgesia and microglial activation associated with BDNF-Trkb signalling." (PMID 35382731, 2022). "We suggest that the effectiveness of P2X4Rs in migraine progression may be due to the promotion of the synthesis and release of BDNF in microglia." (PMID 31937253, 2020).
migraine (continued). "Meanwhile, in a study of migraine populations both genotype and allele frequencies of BDNF rs2049046 were not significantly different, although the heterozygous AT genotype at this SNP was associated with the increased risk of migraine." (PMID 32859253, 2020). "Mechanisms for migraine prevention by exercise may include increased beta-endorphin, endocannabinoid and brain-derived neurotrophic factor levers in plasma after exercise." (PMID 30203180, 2018). "In addition, serum levels of BDNF were found increased in migraineurs compared to healthy controls or during migraine attacks compared to pain-free periods." (PMID 28507530, 2017). "Although BDNF had significant reduction in headache-free intervals of migraine relative to migraine attack (P<0.05), BDNF in headache-free intervals was higher than that in non-migraine control group (P<0.05)." (PMID 27875242, 2017). "This study, showing a correlation between migraine and BDNF, supports the hypothesis that BDNF has a role in the pathophysiology of migraine." (PMID 23815568, 2013). "This is the first study to show elevation of BDNF in both migraine and cluster patients." (PMID 22584531, 2012). "Moreover, manipulating BDNF gene expression may contribute to developing other disorders or diseases, including anxiety, depression, refraction, and chronification of migraine." (PMID 36454123, 2023). "Recently, we suggested that an interplay between secretory autophagy in microglia and degradative autophagy in neurons may play a role in migraine pathogenesis with the involvement of brain-derived neurotrophic factor (BDNF) and the interaction of ATP with the purinergic receptor P2X7 (P2X7R)." (PMID 38068855, 2023). "Therefore, using the genetic depletion of BDNF from microglia or neuron animals may provide a good model to evaluate the role of BDNF in migraine or other animal models of pain." (PMID 31937253, 2020). "Thus, the increased BDNF level might mediate NTG-triggered migraines probably through inducing trigeminal sensitization and activation." (PMID 27875242, 2017). "Our study supports the hypothesis that BDNF has an important role in migraine pathophysiology." (PMID 22584531, 2012). "SCFA treatment decreases nitric oxide, brain-derived neurotrophic factor (BDNF), and neurotrophin-3 in the intestine of mice with NTG-induced migraine." (PMID 36173071, 2024). "The most studied within the migraine field are the neurotrophins NGF and BDNF; however, it should be noted that changes in other growth factors were also reported in migraine sufferers." (PMID 36982428, 2023). "Female ovariectomized rats showed significant reduction in the expression of BDNF, TrkB, p-CREB and p-ERK in both attacks and intervals of NTG-induced migraine, relative to rats that have their ovaries." (PMID 27875242, 2017). "Thus, BDNF may also be involved in the generation and/or modulation of migraine." (PMID 27875242, 2017). "BDNF/TrkB and ERK/CREB axes facilitate migraine attacks probably via sensitization of pain-sensing neurons (e.g. nociceptive neurons) in trigeminal nucleus caudalis and somatosensory cortex." (PMID 27875242, 2017). "This study initially investigated the involvement of BDNF, TrkB, p-ERK and p-CREB in the migraine attacks that were induced by nitroglycerin (NTG) injection in rats." (PMID 27875242, 2017). "To understand the function of BDNF, TrkB, ERK and CREB in migraine, we initially mapped their expression in the brain of rats that were subjected to injection with NTG or vehicle." (PMID 27875242, 2017). "Collectively, this study unveiled a positive correlation of BDNF/TrkB and CREB/ERK axes in NTG-induced migraine and the promoting effects of estrogen on their signals in the migraine." (PMID 27875242, 2017). "Collectively, this study unveiled a positive correlation of BDNF/TrkB and ERK/CREB axes in NTG-induced migraine and promoting effects of estrogen on their signals in the migraine." (PMID 27875242, 2017).